CD36 (CD36 molecule (CD36 blood group))
Diseases named in the same sentence as CD36 in open-access papers (continued):
Sharing a sentence is not in itself a finding about the gene and the disease.
cancer (continued). "In addition, cancer cells can undergo metabolic adaptation, such as increased expression of CD36 to leverage on the adipose microenvironments, leading to high levels of fatty acid uptake and oxidation, besides resulting in chemotherapy resistance." (PMID 38643249, 2024). "Importantly, these results highlight the potential of implementing CD36/CD47 as dual markers to select patients for VT1021 treatment in a broad range of cancer indications." (PMID 39627379, 2024). "CD36 is highly expressed in many types of cancer cells and also promotes cancer progression." (PMID 38276607, 2024). "In cancer cells, CD36 could also regulate cell proliferation, glycolysis, and Epithelial-Mesenchymal Transition (EMT) through the MAPK, AKT, and STAT3 signaling pathways to determine the physiological and pathological processes of cells." (PMID 38881887, 2024). "CD36 could be expressed on the surface of various cell types including monocytes, macrophages, cancer cells, endothelial cells and platelets." (PMID 38881887, 2024). "Subsequent analysis focused on pan‐cancer studies of the two core prognostic genes, CD36 and MYD88." (PMID 38742843, 2024). "Both FABP4 and CD36 have been suggested as emerging therapeutic targets for cancer." (PMID 38748262, 2024). "Moreover, we provide an overview of the latest anti-CD36 cancer therapies, thus opening new perspectives for future personalized medicine." (PMID 38370376, 2024). "Currently, many studies have shown that CD36 can be used as a potential target for cancer therapy." (PMID 38276607, 2024). "CD36, a lipid transporter, is highly expressed in certain kinds of cancer cells." (PMID 38276607, 2024). "Throughout cancer progression, FAs flow into cancer cells via lipid transporters, exemplified by CD36, which is ubiquitously expressed in various cell types, including platelets, mononuclear phagocytes, adipocytes, hepatocytes, myocytes, and certain kinds of epithelial cells." (PMID 38276607, 2024). "CD36-driven fatty acid metabolism is indispensable in the development of cancer." (PMID 38319449, 2024). "Therefore, as a therapeutic target in cancer immunotherapy, strategies targeting CD36 have garnered great interest." (PMID 39273384, 2024). "The function of CD36 in cancers has been well studied in multiple reports." (PMID 39627379, 2024). "Co-culture with adipocytes improved cancer cell lipid catabolism through the CD36/CPT1 pathway." (PMID 38511770, 2024). "Other than that, numerous findings indicated that CD36 depletion in cancer cells could inhibit their growth when combined with approaches that inhibit de novo FA synthesis." (PMID 36675817, 2023). "Although the O-GlcNAcylation of CD36 has also been reported in cardiomyocytes, it remains unclear how prominent role O-GlcNAcylation plays to regulate CD36 functions in other cell types and cancers." (PMID 37371076, 2023). "Reduced FAO and downregulation of PPARA the master regulator of lipid catabolism have also been linked to susceptibility to ferroptosis in other cancer models while increased uptake of PUFA via CD36 has been shown to trigger ferroptotic cell death/susceptibility in T cells." (PMID 37059720, 2023). "Also, S100A8 and S100A9 were down-regulated after CD36 knockdown, which are classical ligands related to cancer aggressiveness." (PMID 37207149, 2023). "In addition to its expression and activity in cancer cells, CD36 also has important implications in several intratumoral immune populations, where it likely contributes to treatment failure due to the development of an immunosuppressive TME." (PMID 37371076, 2023). "Previous studies have demonstrated that CD36 levels are upregulated in some malignancies, such as ovarian cancer, breast cancer, gastric cancer, oral cancer, melanoma, and colorectal cancer, to maintain cancer cell progression and metastasis." (PMID 37056351, 2023).
cancer (continued). "This review will summarize the role of CD36 in promoting the growth and stemness of cancer cells, providing energetic support for metastasis, mediating the acquisition of drug resistance to a wide range of therapeutic agents, and facilitating immune suppression in the TME." (PMID 37371076, 2023). "However, the functional significance and prevalence of CD36 acetylation in cancer remain uncharacterized." (PMID 37371076, 2023). "Fatty acid translocase CD36 is the predominant fatty acid transporter in cancer cells." (PMID 37277821, 2023). "Together, these studies highlight that FA metabolism appears to be an essential fuel source for metastasis, although cancer cells could evolve a variety of different mechanisms, in both CD36-dependent and -independent manners, to meet their metabolic demands." (PMID 37371076, 2023). "Last but not least, CD36 increased expression is associated with the upregulation of survivin, a protein which has been demonstrated to support cancer cell progression and resistance to therapy." (PMID 37760840, 2023). "Importantly, CD36 has also been previously reported to lack glycosylation in several mouse and human cancer cell lines under basal culture conditions, indicating a probable defect in cell surface localization and FA uptake activity in these cells." (PMID 37371076, 2023). "Therefore, the deleterious effects of CD36 in cancer are likely due to increased expression and activity rather than the gaining of function mutations." (PMID 37371076, 2023). "All in all, whether Parkin, USP10, USP14, or UCHL1 plays a role in the regulation of CD36 protein stability in cancer cells remains poorly understood." (PMID 37371076, 2023). "Similarly, CAFs promotes colon cancer cells to absorb lipids secreted from CAFs through CD36, thereby promoting cancer cell migration." (PMID 37700339, 2023). "Primary adipocytes could induce ovarian cancer cells to express CD36 which enhances the fatty acid uptake and lipid droplet accumulation of cancer cells." (PMID 37277821, 2023). "It is generally believed that CD36 is a potential biomarker and therapeutic target for cancer." (PMID 37978381, 2023). "While several studies have reported that CD36 is expressed at the glycosylated ~88kDa size in cancer cells, it might be worth revisiting the glycosylation status and/or cellular localization of CD36 in future studies." (PMID 37371076, 2023). "The transcriptional upregulation of CD36 has been well documented in other cancers." (PMID 37371076, 2023). "Several studies also suggest that CD36 is over-expressed and drives progression in several cancers." (PMID 37612265, 2023). "FA uptake is critical in supplying cancers with exogenous FAs for their progression; therefore, targeting the FA transporter CD36 could represent a promising strategy for treating some of these gynaecological cancers." (PMID 35448537, 2022). "Thus, the TME appears to take advantage of CD36 fatty acid transport functions to manipulate surrounding innate immune cells such as TAMs and MDSCs to avoid immune activation against cancer cells." (PMID 35438721, 2022). "In addition to FABP4, CD36 appears as an interesting metabolic target to limit metastatic progression in cancer." (PMID 35945203, 2022). "To directly test whether the reduction of the NSUN3-deficient metastasis-initiating population was due to the downregulation of CD36 rather than the loss of the mitochondrial RNA modifications, we stably overexpressed CD36 in NSUN3-depleted cancer cells." (PMID 35768510, 2022). "CD36-targeting antibodies are also effective in other models of cancer." (PMID 36568966, 2022). "Reported changes in cancer cellular functions by CD36 activation." (PMID 36568966, 2022). "An emerging role of CD36 in cancer has been proposed in recent years." (PMID 36184646, 2022). "Pharmacological silencing of CD36 has also shown positive results in cancer models." (PMID 36568966, 2022).
cancer (continued). "CD36, also known as fatty acid translocase, transports fatty acids into cells and thus plays an important role in regulating the growth, metastasis and epithelial–mesenchymal transformation of many cancers." (PMID 36038892, 2022). "Moreover, CD36 mediates immunological recognition, inflammation, cell adhesion, and apoptosis in pathogenesis of cancer." (PMID 36085041, 2022). "CD36, fatty acid transport protein family (FATPs), and plasma membrane fatty acid-binding proteins (FABPpm) all exacerbate the aggressiveness, growth, and survival of cancer cells." (PMID 35745875, 2022). "CD36 is overexpressed in various cancer cells and is critical for cancer cell metastasis." (PMID 36588702, 2022). "However, CD36 is also expressed by cancer cells, in which its glycosylation is relatively low, and the function is debated." (PMID 35991116, 2022). "However, CD36 mRNA is significantly lower in CRC cancer tissues in the TCGA database or in studies available in GEO." (PMID 36568966, 2022). "Of interest is the observed downregulation of CAV1 and CD36, both of which are involved in lipid metabolism and metabolic reprogramming of MDSC, and mycobacterial infections, and are associated with poor clinical outcomes in malignant tumors." (PMID 35356003, 2022). "CD36 has a significant role in cancer progression, spread, and metastasis." (PMID 36132984, 2022). "To summarize, CD36 can synergize the pro-cancer effects of TAMs via multiple mechanisms, suggesting that targeting CD36 to modulate the oxidation and polarization of TAMs may be an effective therapeutic strategy." (PMID 36354702, 2022). "Increased FASN, CPT1B, and CD36 expression correlate with poor drug response in cancer patients." (PMID 35764645, 2022). "There is also evidence of a positive correlation between CD36 expression/activation and EMT induction in cancer cells, where CD36-mediated FA uptake/accumulation and the consequent energetic reprogramming are key for the acquisition of a more aggressive phenotype." (PMID 36568966, 2022). "Inhibiting CD36 in PCa could reduce the uptake of fatty acids, cell proliferation, and cancer aggressiveness." (PMID 35884514, 2022). "Clinical studies targeting CD36 signaling in cancer are underway." (PMID 35991116, 2022). "It has also been indicated that CD36 promotes cancer progression by activating PI3K/AKT signaling." (PMID 34459127, 2021). "Above all, CD36 expression was negatively correlated with TNB in most cancer types." (PMID 34234847, 2021). "Furthermore, CD36 mRNA levels positively correlate with epithelial-mesenchymal transition (EMT) in several cancers, including PCa." (PMID 34386430, 2021). "CD36 is one of the most well-characterized receptors of fatty acids in cancer cells." (PMID 33401771, 2021). "The present study found CD36 expression and its prognostic value in multiple cancer types." (PMID 34234847, 2021). "As a result, the expression of CD36 presented high heterogeneity among most of the cancer cell lines, which might reflect its influence on the malignant behaviors of cancer cells." (PMID 34234847, 2021). "Interestingly, TSP-1, a known ligand of CD36 that inhibits angiogenesis by ECs, was unable to inhibit VM formation by the cancer cells." (PMID 34215227, 2021). "The loss of CD36 (via siRNA knockdown) did not impact on the cancer cells being able to invade up to 150 μm." (PMID 34215227, 2021). "Various studies have reported the potential for CD36 and FABP4 to be targeted for therapy in different cancers, indicating that targeting either CD36, FABP4 or both may provide therapeutic opportunities." (PMID 34561446, 2021). "Moreover, CD36 expression presented a disease-specific association with CD274 (PDL-1) and CTLA4 among different cancer types." (PMID 34234847, 2021). "Taken together, this data suggests that CD36-expressing VM-competent cancer cells may utilize CD36 differently to ECs for the formation of vascular structures; a process that is yet to be fully elucidated." (PMID 34215227, 2021).
cancer (continued). "CD36 expression was significantly correlated with the 6 immune infiltrates in most cancer types." (PMID 34234847, 2021). "CD36-mediated exogenous fatty acid uptake and oxidation leads to cancer growth and metastasis." (PMID 33771982, 2021). "However, the association of CD36 expression with CD274 (PDL-1) and CTLA4 was inconsistent among different cancer types." (PMID 34234847, 2021). "However, the association of CD36 expression with CD274 (PDL-1), TIGIT, and TNFRSF25 was cancer type-specific." (PMID 34234847, 2021). "Recent studies suggest that the CD36 on the cancer cell surface plays a role in LCFA uptake." (PMID 34314388, 2021). "However, BODIPY-FL-C16 uptake by cancer cells was only marginally higher upon WT CD36 expression compared with cysteine-mutant CD36-expressing cancer cells." (PMID 34314388, 2021). "With CD36 knockdown, there is a 50% reduction in cancer cells at this position." (PMID 34215227, 2021). "In addition to prognostic value, the association between CD36 alterations and 6 immune infiltrative cells (B cells, CD4+ T cells, CD8+ T cells, dendritic cells, macrophages, and neutrophils) across different cancer types was analyzed." (PMID 34234847, 2021). "Among the proteins participated in FAs uptake, CD36 is a dominating player in metabolic tissues which increases long chain fatty acids uptake and has a unique role of initiating the metastasis in many types of cancers." (PMID 35003369, 2021). "CD36 protein is mainly located in the membrane of cancer cells." (PMID 34234847, 2021). "However, more clarifications are needed to verify the exact contribution of CD36 and Lox-1 in cancer progression." (PMID 34063116, 2021). "Finally, CD36 has been reported to form a complex withannexin-A2 and prohibitin-1, both of whichhave reported roles in cancer." (PMID 34603769, 2021). "Moreover, malignant tumors also exhibit increased expression of CD36, which facilitates increased fatty acid uptake from outside of the cell, which promotes the EMT process." (PMID 33801564, 2021). "The fatty acid receptor CD36 is emerging as a potential strategy for cancer treatment." (PMID 33771982, 2021). "In addition, CD36 is expressed by dendritic cells and mediates antigenpresentation, which is important to consider in the context of cancer immunology." (PMID 34603769, 2021). "Notably, caution surrounding CD36 as a target to treat cancer is unsurprising given that it is a fatty acid scavenger receptor with a wide range of ligands." (PMID 34215227, 2021). "CD36 expression presented significant prognostic value across multiple cancer types." (PMID 34234847, 2021). "CD36 expression significantly affects prognosis in the six cancer types." (PMID 34234847, 2021). "A possible emerging role of CD36 in cancer has been proposed recently." (PMID 33771982, 2021). "CD36-induced potential of metastasis was reported to depend on lipid metabolism in cancer cells." (PMID 32781778, 2020). "Interestingly, the expression of CD36 in cancer cells is also able to regulate the metabolic crosstalk with TME by increasing their dependency on exogenous lipid uptake." (PMID 32486505, 2020). "Blockade of TGF-β2 signaling reduced plasma membrane-associated CD36 expression and using a fluorescent palmitate analog (BODIPY-conjugated C16), we confirmed the increased capacity of FA uptake by TGFβ2-stimulated native cancer cells." (PMID 31974393, 2020). "However, due to its multi-functional role, the potential metastasis-promoting activity of CD36 in GC and other cancers remains to be fully characterized." (PMID 33232276, 2020). "Adipocytes upregulate CD36 and drive cancer cells to gain CSC-like features." (PMID 32731620, 2020).
cancer (continued). "Moreover, targeting FA uptake using an antibody against CD36, a major transporter for exogenous FAs into the cells, reduced cancer severity in patient-derived xenografts, and CD36 deletion slowed cancer progression in prostate-specific PTEN-/- mice." (PMID 32686647, 2020). "Based on the data presented, one may consider that there are just a few studies on CD36 expression in normal pancreatic tissue and cancer." (PMID 32781778, 2020). "Importantly, inhibition of either FA uptake by CD36 blocking antibodies or FA mitochondrial metabolism by CPT1 inhibitor etomoxir significantly reduced Smad2 acetylation in 6.5/cancer cells." (PMID 31974393, 2020). "CD36 has been demonstrated to uptake free fatty acids from the extracellular microenvironment to provide substrates for energy production and the synthesis of macromolecules supporting cell growth, proliferation, survival, and invasion in cancer." (PMID 33050166, 2020). "This is an important finding given the key role of CD36 in cancer." (PMID 33123499, 2020). "Knockdown of CD36 can also diminish adipocyte-mediated invasion and migration of cancer cells." (PMID 33194756, 2020). "The results indicated that CD36 could enhance anti-apoptosis protein expression, which contributed to gemcitabine resistance by protecting cancer cells from drug-induced cell death." (PMID 32781778, 2020). "Fatty acid translocase, also known as CD36, is the predominant fatty acid transporter in many normal cell types, including adipocytes, cardiac myocytes, enterocytes, and skeletal myocytes and also in cancer cells." (PMID 31769430, 2019). "An overlooked area of research is the involvement of CD36 methylation in the onset of cancer." (PMID 31379931, 2019). "Indeed, CD36 deletion in a prostate cancer animal model revealed a dramatic decrease in fatty acid uptake and ameliorated cancer progression." (PMID 31847240, 2019). "In addition, CD36+ cancer stem cells, which have multiple functions in promoting cancer progression, have been correlated with cancer initiation, chemotherapy resistance, and self-renewal activity." (PMID 31655604, 2019). "CD36, a cell surface receptor, mediates the uptake of exogenous FAs including PA, and has been demonstrated to contribute to the initiation and progression of multiple types of cancers." (PMID 30717785, 2019). "Thus, in terms of epigenetic control of CD36, there are still many gaps to be filled, especially in cancer research." (PMID 31379931, 2019). "Interestingly, cancer cell spheroids with higher CD36 levels showed stronger migration and invasion capabilities." (PMID 31410220, 2019). "Importantly, significantly more CD36-positive cancer cells were observed to be present in lymph node metastatic foci than in primary tumors." (PMID 31410220, 2019). "In ovarian cancer, cervical cancer, hepatocellular carcinoma, gastric cancer, elevated fatty acids absorption by CD36 could drive cancer progression and metastasis." (PMID 31484922, 2019). "In this respect, we wondered the different roles of CD36 in primary CRC might result from adaptive metabolic changes by cancer cells to sustain their viability." (PMID 31484922, 2019). "Although histone modifications have been documented extensively in cancer, no study has yet linked CD36 histone marks with tumorigenesis." (PMID 31379931, 2019). "Data gathered in preclinical models of various cancers have shown that blocking CD36 might prove beneficial in stopping metastasis spread." (PMID 30069479, 2018). "Data gathered in preclinical models of various types of cancers taught that blocking CD36 might prove beneficial in stopping metastases from spreading." (PMID 30069479, 2018). "Enhancement of CD36 expression or function is also involved in progression of other cancer types." (PMID 30573731, 2018). "Some studies suggest that fatty acid uptake via CD36 may promote cancer cell migration and proliferation." (PMID 29914089, 2018).